IL4 (interleukin 4)
Diseases named in the same sentence as IL4 in open-access papers (continued):
Sharing a sentence is not in itself a finding about the gene and the disease.
infection (continued). "Once we characterized the cell populations and the phenotype obtained with the stimulation with TNF-α + IFN-γ or IL-4, we proceeded to analyze the effect of the infection of BMMΦ and neonatal mouse cardiomyocytes with two different T. cruzi isolates in the modulation of L-arginine metabolism." (PMID 39452749, 2024). "Notably, IL-5 and IL-4 levels were also reduced in these mice, suggesting enhanced resistance to infection." (PMID 39635124, 2024). "In addition, Th2 cytokines including IL-4 and IL-5 were also decreased in Ifngr1-/- mice following infection, suggesting the downregulation of both type 1 and 2 immune responses in the absence of IFN-γ signaling." (PMID 38743761, 2024). "Notably, the hepatic expression of type I and type II cytokines like Tnfα, Ifnγ, Il12, or Il4, as well as regulatory cytokines like Il10, showed maximum expression at the youngest age of infection similar to egg load and granuloma extent." (PMID 39404406, 2024). "In the present study, MXSGD + SJZD may enhance the antiviral effect by modulating the immune response by promoting the expression of Th1 cell-derived TNF-α and IFN-γ and Th2 cell-derived IL-4 at a late stage of FM1 infection." (PMID 39221016, 2024). "Imad and colleagues studied the cytokine profile of 96 hospitalized adult patients admitted to the Hospital for Tropical Diseases, Bangkok, Thailand, during 2015–2016, which showed the increased expression of protein interleukins (IL-4, -6, -8, -10), TNFα, and IFNγ during infection." (PMID 39200005, 2024). "However, in the present study, IL-4 levels remained high throughout the infection in patients in the death group, making IL-4 a significant predictor of mortality." (PMID 39408907, 2024). "Furthermore, neonatal mouse cardiomyocytes stimulated with IL-4 showed an increased arginase activity (more than 75 U/mg of protein), which diminished significantly and in a similar magnitude during infection with either of the T. cruzi isolates." (PMID 39452749, 2024). "of ruminants can provoke serious health problems and because the infected host may modulate the infection through the activity of IL4, IL5, IL13, and the FCεR1A receptor genes." (PMID 39057830, 2024). "In addition to increased intestinal permeability, we observed increased bacterial 16S copies in blood of baso IL-4/IL-13 (−) mice relative to genotype controls following infection." (PMID 38780542, 2024). "The study indicated that zebrafish infected with A. hydrophila showed increased IL-10 and IL-4 expressions in the early stages of infection to alleviate inflammation, decreased in subsequent stages after successfully mitigating the bacteria, and later increased again to maintain body homeostasis." (PMID 39185043, 2024). "Furthermore, IFN-γ and IL-4 in rat serum were significantly higher than in mouse serum at two weeks post-infection, indicating significantly different immune responses in the brains of rats and mice." (PMID 38805557, 2024). "In G6, IL-2, IL-12, IL-4, and IL-5, involved in the growth, proliferation, and differentiation of Th1 and Th2 cells, were notably less expressed in the early days post-infection compared to G1a, where an expression level comparable to or higher than the controls was observed." (PMID 38891666, 2024). "However, compared to Tg infected animals, HpTg infected animals only had decreased levels of MLN Ifnγ and SI2 Il-10 at day 5 post Tg infection, despite increased Il-4 and Il-13 in the SI, PP, MLN and SPL." (PMID 38950025, 2024). "IL‐4 is a Th2‐cell‐type cytokine that protects against infection and promotes tissue regeneration." (PMID 38037457, 2024). "Thus, CD4+ T cell-secreted IL-4 and IL-5 can enhance both the primary B cell responses to vaccination and future responses to infection or vaccination." (PMID 38543915, 2024). "IL-4 has the capacity to induce B cell proliferation and Th2 differentiation and switch the immunoglobulin (Ig) class of IgE and IgG4 to play a critical role in inflammation and infection." (PMID 38349864, 2024).
infection (continued). "In contrast, the maternal cytokine response to vaccinated infection is not centered on interferons, but rather IL4, strongly associated with Th2 responses." (PMID 39845965, 2024). "Moreover, the Th2-specific cytokine Il4 and the immunomodulatory cytokine Il10 were induced with infection and most pronounced when the infection occurred at an early age." (PMID 39404406, 2024). "However, during the muscle stage of infection, there was a shift towards a Th2 response, characterized by the production of cytokines such as IL-4, IL-10, and IL-13, which were involved in regulating inflammation and tissue repair." (PMID 38166140, 2024). "IL-4 can induce the polarization of macrophages toward the M2 phenotype, which is permissive to the proliferation and dissemination of C. neoformans and promotes infection of the host by C. neoformans (34, –, 38)." (PMID 39287443, 2024). "For example, recombinant surface antigen SAG1 (rSAG1) reduced fetal infection in resistant mice, but not in susceptible animals, although similar levels of cytokines such as IL-4, IL-10, and IFN-γ were observed in maternal sera during gestation." (PMID 39597754, 2024). "infection could induce IL-4 secretion by eosinophils and eosinophils-derived IL-4 mediate the inhibition of CD8+ T cell apoptosis during early stage of L.m." (PMID 38413575, 2024). "We next addressed whether IL-4 derived from eosinophils during early infection was responsible for maintaining the quantity of memory CD8+ T cells." (PMID 38413575, 2024). "IL-4, a typical type 2 cytokine, usually dampens immune defense and amplifies infection." (PMID 39287443, 2024). "This was accompanied by changes in cytokine profiles and parasite loads which were dependent on the cell type (CD4+ T, CD8+ T, NK, NKT and γδ T cells), the organ (SI, PP, MLN, SPL and liver), the time-point (day 5 and 10 post-infection) and the cytokine (IFNγ, IL-4, IL-10 and IL-13) studied." (PMID 38950025, 2024). "However, long-term infection drives the immune system towards a Th2 response with high levels of IL-4, IL-5, IL-13, and immunosuppressive IL-10 and TGF-β, leading to tolerance." (PMID 38817444, 2024). "On the other end of the spectrum are IL-4 and IL-13, which are associated with a Th2 response and, therefore, with susceptibility to infection by not activating macrophages properly." (PMID 39211053, 2024). "Similarly, high IL-2 and IL-4 levels have been reported in children with severe CAP, indicating that severe infection, like that seen in our study, is associated with elevated cytokine levels." (PMID 39737297, 2024). "However, the actual expression of IL-4 and IL-5 proteins returned to the levels in naïve Th2 cells at 40 days post-infection and further decreased at 60 days post-infection." (PMID 38788198, 2024). "The mild expression change of IL-4 (IL-4I1, Fc.: 1.25×) was in accordance with the findings of other authors, while the decreased expression of IL-8 (IL-8, Fc.: −2.74×) by the 3rd hour of infection is seemingly in contrast with an earlier finding." (PMID 38787238, 2024). "Regarding Arg-2 expression, even though it was induced in neonatal mouse cardiomyocytes stimulated with IL-4, interestingly, the infection with both T. cruzi isolates diminished the expression of the enzyme to the extent that it was not possible to detect it by Western blot." (PMID 39452749, 2024). "In infectious diseases, IL-4 exhibits a dual function: while it can protect against certain infections by stimulating antibody production and eosinophil activity, it can also hinder the elimination of intracellular pathogens by suppressing Th1 responses and macrophage activation." (PMID 38251210, 2024). "The results demonstrated that, influenced by the liver parasitic infection, pro-inflammatory factors IL-1β and TNF-α exhibited continuous increases in both serum and liver levels at all infection stages, while anti-inflammatory factors IL-4 and IL-10 showed persistent decreases." (PMID 39749332, 2024).
infection (continued). "Furthermore, it resulted in decreased levels of Th2 cytokines (IL-4, IL-5, and IL-13) after infection, while interferon γ levels remained largely unchanged." (PMID 38016013, 2024). "Similarly, when analyzing cytokine production upon PMA/Ionomycin stimulation, a steady increase in IFN-g+ CD4+ T cells from 1-4 weeks post-infection, and only a minor shift in IL-4+ CD4+ T cells around 2 weeks post-infection was detected." (PMID 38799456, 2024). "After infection, animals generate IL-4, IL-5, and IL-10, resulting in a Th2 response." (PMID 37110723, 2023). "Increased levels of IL-4 and IL-13 in late-phase infection (12 wpi) were detected in serum; these exhibited synergy, which may be associated with M2 activation for damaged tissue repair." (PMID 37152685, 2023). "This hypothesis is further strengthened by the finding that the depletion of L-arginine from cell culture media resulted in unchanged S.tm levels, even when stimulated with IL-4 after infection." (PMID 37190073, 2023). "Importantly, the high IFN-γ levels were sustained during infection while increasing production of IL-4 and IL-10 was also detected." (PMID 37631952, 2023). "Thus, it is tempting to assume that the increase in polyamines in unpolarised BMDM stimulated with IL-4 after infection with S.tm is primarily driven by the metabolisation of L-arginine by IL-4-dependent ARG1." (PMID 37190073, 2023). "Furthermore, C. jejuni was shown to induce IL-4 production in the mouse colon 5 weeks after infection." (PMID 36979384, 2023). "In addition, it has been shown that worms from unisexual infection are able to prime T helper cells and basophils to produce IL-4 and thus have an important role in the establishment of a Th2 immune milieu." (PMID 36923416, 2023). "It was found that at day 9 post-infection, the inflammatory cytokines IL-12, IL-17 and IL-6 were significantly decreased (p < 0.05), while immunosuppressive mediator IL-4 was increased (p < 0.05) in MS1987-infected mouse lung compared with MSVec-infected mouse lung." (PMID 38029253, 2023). "The infection of bacteria or viruses can trigger type I pro-inflammatory immune responses (e.g., IFN-γ, TNF-α, TH1 cells), whereas infection by helminths typically elicits a type II host resistance and tolerizing immune response (e.g., IL-4, IL-5, IL-13, TH2 cells)." (PMID 37789420, 2023). "Additionally, the levels of anti-inflammatory cytokines IL-4 and IL-10 tended to increase at all time points, with significant increases in IL-4 at the 15 and 20 weeks of infection (P < 0.05)." (PMID 38076459, 2023). "Importantly, we found that unpolarised macrophages which are exposed to IL-4 after establishment of infection with S.tm are able to better control bacterial multiplication." (PMID 37190073, 2023). "However, Th2, when producing IL-4, suppresses the Th1 response and worsens the course of the infection, contributing to its spread." (PMID 37761328, 2023). "ARG1 is a cytoplasmic enzyme that is expressed in macrophages, bone marrow-derived suppressor cells, dendritic cells, and innate lymphoid group 2 cells in response to Th2-type cytokines (IL-4 and IL-13) and infection with pathogens related to other signaling factors." (PMID 36918848, 2023). "However, IL-4 induces the polarization of Th0 to the Th2 subset, and the production of IL-4 and IL-10 inhibits the anti-infection process and leads to the dissemination of M. tuberculosis." (PMID 38140143, 2023). "Depletion of L-arginine reversed the protective effect of IL-4 toward infection control." (PMID 37190073, 2023). "Overexpression of IL-13 in C57BL/6 mice, which are typically resistant to Leishmania major infection, renders them susceptible to infection, irrespective of IL-4 expression." (PMID 37908348, 2023). "However, significant differences were noticed in the levels of regulatory cytokines IL-10 and IL-4, wherein M.smeg::MtbEspR infection showed higher cytokine titers, clearly pointing to an inclination towards Th2 immune response." (PMID 37928551, 2023).
infection (continued). "The cytokines produced by the anti-inflammatory CD4+ Th2 cells, which include IL-4, IL-5, and IL-13, lead to the growth of the parasite and the persistence of infection in chronic diseases, in addition to playing a role in the negative regulation of the oxidative burst in infected macrophages." (PMID 37235324, 2023). "Furthermore, it was shown that this depends on the differentiation status of macrophages, as only unpolarised macrophages which were supplemented with IL-4 show a better infection control by impacting the L-arginine pathway." (PMID 37190073, 2023). "However, while differentiation of macrophages with IL-4 impairs host resistance to the intracellular bacterium Salmonella enterica serovar Typhimurium (S.tm), little is known on the effects of IL-4 on unpolarised macrophages during infection." (PMID 37190073, 2023). "Interestingly, IL-4 stimulation after infection (post-stimulation) markedly reduced intracellular bacterial numbers over a period of up to 24 h." (PMID 37190073, 2023). "In addition, mice lacking Klf4-dependent cDC2s show reduced survival by week 7 of S. mansoni infection, comparable to infection of IL-4−/− mice, implying an inability to induce a type-2 immune response." (PMID 37012228, 2023). "Moreover, after infection for 8–10 days, the nILC2s in the lung were significantly increased, with high expression of IL-13 and IL-5, as well as a small amount of IL-4." (PMID 37173731, 2023). "Similarly, IFNγ treatment of unpolarised macrophages after establishment of infection led to higher S.tm CFU in BMDM as compared to IL-4 stimulation." (PMID 37190073, 2023). "When the change over the weeks was examined, the results showed that the CRP changed significantly in the infection group (p = 0.004) and nearly significantly in the hospital group (p = 0.063) and so did the IL4 in the healthy group (p = 0.007) and in the hospital group (p = 0.031)." (PMID 37762523, 2023). "This dynamic study of F. gigantica-infected buffalo serum cytokines has revealed that, in the early stages of both primary and secondary infection, Th2/Treg dominated response was induced; this was manifested in increases of IL-4, IL-5, IL-10, IL-13, and TGF-β and reduction of IFN-γ and IL-17." (PMID 37152685, 2023). "Therefore, a higher level of IL4 would be expected during the early stages of an infection as IL4 would be released to regulate the inflammatory process." (PMID 37762523, 2023). "Next we tested whether regulation of cytoprotective proteins or levels of ROS production could be responsible for the increased infection control by IL-4." (PMID 37190073, 2023). "Additionally, there was a significant decrease production of 13.8-fold in IL-4, 21.3-fold in IL-5, and 12.6-fold in IL-13 at day 90, compared to the highest levels observed at 30 days of infection." (PMID 37691941, 2023). "Transfection of THP-1 cells with the pC-EspR could only marginally increase IL-4 transcript levels, but a 3-fold increase was observed during infection." (PMID 37928551, 2023). "Importantly, priming of macrophages with IL-4 (pre-stimulation) increased Arg1 expression compared to BMDM stimulated with IL-4 after establishment of the infection." (PMID 37190073, 2023). "However, once the infection is treated and the accompanying inflammatory process reduced, the levels of IL4 should decrease." (PMID 37762523, 2023). "DHAV infection could lead to the different expression of various cytokines in young ducklings; for example, the transcription of IL-1β, IL-2, IL-4, IL-6, IL-8, and IL-10 was highly stimulated after infection." (PMID 37391858, 2023). "Also in line with our results from pre-patent infection, a significant reduction in expression of Th2 cytokines IL-4, IL-5 and IL-13 was observed in cDC2 depleted Cre+ mice as a proportion of CD4+ T cells, and as absolute number for IL-5 and IL-13." (PMID 37012228, 2023).
infection (continued). "Specifically, while LmexWT inoculated hamsters developed a disease promoting cytokine response, as evident by the elevated IL-10 and IL-4 expression levels, LmexCen−/− immunized hamsters displayed a diminished expression of both these cytokines relative to LmexWT infection." (PMID 36463228, 2022). "Furthermore, at the protein level, we also confirmed that all four Th2 cytokines (IL-4, IL-6, IL-10, and IL-13) were progressively enhanced in both mouse and rat lungs during the late infection phase of AC." (PMID 35617354, 2022). "However, at 39 weeks post-infection, anti-IL-17A mAb treatment significantly enhanced lung IL-4 and IL-22 levels compared to isotype-matched control Ab treatment in the lungs of M. intracellulare-infected mice." (PMID 35363832, 2022). "Furthermore, the depletion of neutrophils inhibits the production of IL-4 and reduces the parasite’s ability to engage in productive cycles of infection and parasite burden, providing a better response to infection." (PMID 35448829, 2022). "However, an effective response against M. tuberculosis is mediated by the activation of the Th1 pathway, and high IL-4 levels will favour infection." (PMID 36296351, 2022). "Again, at different time points of infection (e.g., 12 h, d5 and d6) we observed that the expression of IL-4 was primarily found in CD45+SiglecF+ eosinophils and some other myeloid cells, but not in CD45+SiglecF− ILC2 (D. Barinberg, S. Obermeyer and U. Schleicher, unpublished observation)." (PMID 35894051, 2022). "However, after 13 weeks of infection, IL-4 levels were dramatically decreased in E. multilocularis-infected mice, and conversely, metacestode wet weight was significantly increased." (PMID 34143400, 2022). "None of these studies have looked at the local effect these cytokines (IL-4 and IL-13) may have at the primary site of infection, the epidermis." (PMID 35456017, 2022). "Contrastingly, the IL4 gene expression of the 100 μg of rGP19-immunized mice later infected with E. canis in vivo in this study displayed a positive relationship with IFN on day 14 post-infection period." (PMID 36006302, 2022). "This may be explained by the fact that antibody production requires Th‐2 cytokines such as IL‐4,39, 40 and since the two parasites are able to induce Th‐2 responses, higher levels of antibodies could occur during the course of infection." (PMID 35734341, 2022). "Also, the Att-S74-T3Bo-infected calves developed significant levels of IL-10 at days 3 and 6 post-infection, and IL-4 at day 12 post-infection." (PMID 36466866, 2022). "Moreover, the NE infection group showed lower mRNA expressions of ileal IL-4 and jejunal IL-10 compared to the TA administration group (P < 0.05)." (PMID 35387091, 2022). "Interestingly, Att-S74-T3Bo-inoculated animals showed significant levels of IL-4 at days 3 and 6 post-Vir-S74-T3Bo infection compared to controls." (PMID 36466866, 2022). "The expression level of IFN‐γ, IL‐17, IL‐4, and IL‐10 increased with the duration of infection." (PMID 36169259, 2022). "Indeed, some strains of L. major elicited higher levels of IFN- and a lower amount of IL-4 within two months post infection in BALB/c mice, while under similar conditions, other L. major strains exhibited lower ratios of IFN-/IL-4 in the LN cells culture." (PMID 35090305, 2022). "However, in an experimental infection of humans with Ascaris suum, the level of IL-17A was decreased while IL-4 and TGF-beta were increased." (PMID 35976976, 2022). "As infection progressed to 7, 14, and 21 dpi, we observed marked reductions in multiple cytokines (including interleukin-1 β [IL-1β] and IL-4) and leukocytes (including CD45+ cells and alveolar macrophages) in mar1Δ mutant strain-inoculated lungs compared to WT strain-inoculated lungs." (PMID 35587201, 2022).